INS (insulin)
Diseases named in the same sentence as INS in open-access papers (continued):
Sharing a sentence is not in itself a finding about the gene and the disease.
Insulin resistance (continued). "Insulin is a potent suppressor of adipose tissue lipolysis and the lack of effect of hyperinsulinemia upon adipose tissue interstitial glycerol levels before weight loss is suggestive of insulin resistance." (PMID 18340018, 2008). "The general hypothesis is that "high-salt diet in combination with defects in candidate genes along the insulin signaling and inflammatory pathways predicts susceptibility to high salt-induced insulin resistance in Dahl S rats"." (PMID 18570670, 2008). "Insulin resistance is considered to be a pivotal eventin the increased risk of plaque instability through different pathways.High concentrations of insulin directly increase proinflammatory activities ofleukocytes, which are involved in atherosclerotic plaque instability." (PMID 18604303, 2008). "Salt-induced oxidative stress triggers a powerful inflammatory response that disrupts the insulin signaling pathway and might possibly explain insulin resistance in genetically susceptible populations." (PMID 18570670, 2008). "The results from previous animal studies have shown that nutritional insults during pregnancy and lactation are linked to glucose intolerance via either hyperinsulinemia/insulin resistance, or decreased insulin secretory capacity, depending on the type and timing of the prenatal nutritional insult." (PMID 18928547, 2008). "While obesity is a relative static cause of insulin resistance, characterised by low grade inflammation, we here decided to study the time course of insulin resistance following the acute intervention of cardiac surgery with extracorporeal circulation, which is a known inflammatory stimulus." (PMID 19087258, 2008). "The higher FFA may cause peripheral insulin resistance by interfering with the access of insulin to skeletal muscle or the insulin signaling resulting in reduced glucose transport into muscle." (PMID 18523557, 2008). "Anthropometric measurements (SAD, body mass index [BMI], waist circumference [WC] and waist-to-hip ratio [WHR]; all measured in supine position) and cardiovascular risk factors (C-reactive protein [CRP], insulin, glucose, insulin resistance [HOMA-IR], blood pressure and serum lipids) were assessed." (PMID 17391519, 2007). "The metabolic syndrome definitions that do not require measurement of insulin levels (NCEP, ACE and IDF) identify twice more patients with insulin resistance and increased Framingham risk scores and are more useful than the definitions that require measurement of insulin levels (WHO and EGIR)." (PMID 18088443, 2007). "One reason for the relatively low proportion with elevated glucose may be that insulin resistance is generally associated with increased levels of insulin production." (PMID 17300718, 2007). "We investigated whether peripheral insulin resistance and/or a severe defect in insulin secretion may cause hyperglycaemia in the POKO mouse." (PMID 17465682, 2007). "While insulin resistance is usually associated with decreased adiponectin levels, at least in diabetics, in hyperthyroidism this inverse relationship appears to be lost, and there is a direct correlation of adiponectin with plasma insulin and HOMA-IR." (PMID 16472384, 2006). "Interestingly, in patients with NAFLD, the present study demonstrated a very significant association between A2M and insulin levels, a hallmark of insulin resistance." (PMID 16503961, 2006). "In general, therapies that lower insulin levels and insulin resistance and lead to weight loss may prove useful for treating PCOS." (PMID 16359551, 2005). "Sphingolipid metabolism might impact insulin secretion and has been linked to insulin resistance." (PMID 41133433, 2026). "In EIAS 2 populations of insulin antibodies have been demonstrated: the first with low affinity/high capacity (commonly associated with postprandial hyperglycemia and nocturnal hypoglycemia) and the second high affinity/low capacity (typically accompanied by severe insulin resistance)." (PMID 41472947, 2026).
Insulin resistance (continued). "Moreover, high GI foods like white rice cause rapid increases in blood glucose and insulin levels, leading to hyperinsulinemia, which not only worsens insulin resistance but also promotes the activation of pathways like mTOR and PKC, both of which are involved in pathogenesis of CTRCD." (PMID 40227756, 2025). "Thus, the effect of acupuncture on insulin resistance of PCOS may potentially be linked to the interaction of these lipid species with the insulin signaling pathway." (PMID 41210858, 2025). "However, in rare instances, mutations in the IR gene can cause significant insulin resistance, where affected individuals might need over 100 times the insulin amount typically required by diabetic patients." (PMID 40362446, 2025). "Insulin resistance and inflammation can cause anxiety, and whole grains decrease inflammatory biomarkers and influence the postprandial glucose metabolism, which could affect insulin sensitivity." (PMID 40005010, 2025). "Notably, glycine levels are positively associated with insulin secretion in individuals with Type 2 diabetes, suggesting that this amino acid may play a role in the pathogenesis of insulin resistance." (PMID 40289598, 2025). "However, recent research suggests that the metabolic changes underlying GDM, such as insulin resistance, impaired insulin secretion, or relative insulin deficiency, may be detectable as early as the first trimester (before 14 weeks of gestation)." (PMID 41334337, 2025). "The common type II diabetes mellitus (T2DM), which arises with ageing owing to inadequate insulin secretion from beta cells resulting in insulin resistance, is hypothesised to be associated with late-onset AD through numerous genetic and molecular associations." (PMID 39932549, 2025). "Thus, T1D is caused by autoimmune destruction of β cells, which generally leads to absolute insulin deficiency, including latent autoimmune diabetes of adulthood, while T2D is caused by a progressive loss of adequate insulin secretion by β cells, often in the context of insulin resistance." (PMID 41012462, 2025). "Our findings suggest that among females newly diagnosed with EC, despite having a BMI of 30 or more, a healthier lifestyle may be associated with lower fasting insulin levels and reduced insulin resistance, reinforcing the importance of diet and lifestyle quality." (PMID 41431696, 2025). "Chronic high plasma insulin levels may lead to the desensitization of the insulin receptors and dysregulation of insulin signaling in insulin receptor-expressing tissues, ultimately also causing insulin resistance in the brain." (PMID 41009753, 2025). "Notably, this did not mean MetS is beneficial to beta-cell preservation, since free fatty acids, UA, and related inflammation could cause insulin resistance and a compensatory increase in insulin secretion, which would ultimately damage beta-cell function." (PMID 41141343, 2025). "By enhancing insulin signalling pathways and reducing inflammatory markers, polydatin may help restore normal glucose metabolism and mitigate some of the harmful effects associated with insulin resistance." (PMID 40958722, 2025). "Importantly, this enhanced proliferation of pancreatic β cells could result in elevated insulin secretion upon S961-induced acute insulin resistance that was associated with lower blood glucose." (PMID 40260914, 2025). "It is important to note that, although our observations on the metabolism of these TcMAC21 mice, such as higher insulin sensitivity, align with the only other study assessed metabolic function in these mice, people with DS are at an increased risk for insulin resistance." (PMID 40474784, 2025). "Interestingly, since OC is involved in metabolic regulation, the reduced OC levels in moderate-to-late preterm-born children may be linked to impaired insulin sensitivity and glucose metabolism, potentially increasing their risk of insulin resistance." (PMID 40710563, 2025).
Insulin resistance (continued). "The main pathophysiological process causing hyperglycemia in GDM is a failure of insulin secretion, or relative insulin deficiency, to compensate for insulin resistance, which might be pre-existing, in addition to the insulin resistance elevation during mid to late pregnancy." (PMID 40361947, 2025). "In contrast, miR-20a-5p has been associated with insulin resistance, whereas circulating exosomal miR-20b-5p is elevated in type 2 diabetes and may impair insulin action in human skeletal muscle, suggesting that downregulation with pioglitazone could be clinically beneficial." (PMID 41295241, 2025). "Exposure to hyperglycaemia during pregnancy appears to impair the ability of GDM-MSCs to regulate glucose metabolism and respond to insulin, a finding that may help establish a mechanistic link to the elevated risk of insulin resistance, prediabetes, and T2DM in offspring of mothers with GDM." (PMID 41226805, 2025). "However, prolonged increases in insulin levels may lead to a loss of response from tissues for glucose uptake, which is referred to as insulin resistance, typically observed in T2DM." (PMID 39136514, 2025). "However, none of the enrolled cats had concurrent hypersomatotropism—a condition known to cause severe insulin resistance, which might explain their ability to discontinue insulin therapy." (PMID 40853201, 2025). "In people with obesity, insulin clearance is significantly decreased and inversely associated with insulin resistance in the liver, muscle, and adipose tissue; lower insulin clearance may be an important compensatory mechanism that contributes to hyperinsulinemia in these clinical conditions." (PMID 39998445, 2025). "The consequences of insulin resistance (IR) come from the fact that insulin binding to its receptors diminishes dramatically, and the glucose transport into cells is remarkably affected, causing the decreased bio-utility and bioactivity of insulin in the target organs." (PMID 40943177, 2025). "In addition, insulin resistance, a key driver of type 2 diabetes (T2D), is closely linked to chronic low-grade inflammation and epigenetic alterations affecting glucose metabolism and insulin signaling pathways." (PMID 40243433, 2025). "Two dietary indices, dietary insulin load (DIL) and dietary insulin index (DII), were developed to assess the impact of insulin in foods and record the response to insulin in foods consumed, and these indices could be considered as risk determinants for developing insulin resistance." (PMID 40474898, 2025). "Mitochondrial respiratory capacity has been linked to insulin sensitivity and metabolic flexibility, where excess caloric intake leads to the accumulation of metabolic intermediates, inhibition of glucose and fatty acid uptake from the circulation, and early insulin resistance." (PMID 40318136, 2025). "It has further been demonstrated that glycine enhances insulin secretion directly from human β cells of T2D and non-T2D donors and that circulating levels of glycine are inversely correlated with T2D risk, insulin resistance, impaired glucose tolerance, and obesity." (PMID 40260914, 2025). "Previous studies have focused on insulin resistance as a driving factor in cognitive decline and eventual neurodegeneration associated with obesity; however, in neither females nor males, did peripheral glucose control or central measures of insulin signaling align with cognitive performance." (PMID 38166559, 2024). "According to the accelerator hypothesis growth and excessive weight gain is associated with an increased insulin demand and insulin resistance that accelerate beta-cell apoptosis and autoimmunity in the presence of the susceptibility HLA genotypes leading to T1D." (PMID 37589890, 2024).
Insulin resistance (continued). "As a maintained insulin sensitivity has been reported in the population of the oldest-old, while insulin resistance has been linked with an increased risk for cognitive decline and dementia, including Alzheimer’s disease, Insulin Receptor Binding could be of great interest in aging research." (PMID 38630692, 2024). "In this study, we found that methylation at the CpG4 site of the TGF-β1 promoter may affect PCOS pathogenesis and is more likely to cause insulin resistance than HA; the methylation rate is negatively correlated with fasting insulin level and HOMA-IR in the population." (PMID 38166771, 2024). "In addition, insulin resistance-related pathogenic factors, such as inflammation, might have a role related to both increased insulin levels and decreased arteriolar diameter." (PMID 39661465, 2024). "It is commonly believed that primary insulin resistance, when associated with visceral obesity, is compensated for by increased insulin secretion and reduced insulin clearance; the latter serves to limit compensatory insulin release and prolong the life/function of the β-cell." (PMID 39640841, 2024). "According to these authors, the underlying explanation might be that low insulin secretion and adipose tissue insulin resistance impair the suppression of adipose tissue lipolysis, leading to increased delivery of fatty acids to the liver, where they are stored as triglycerides." (PMID 38397356, 2024). "Therefore, mobilized fatty acids are esterified into triglycerides in the liver, and they may cause insulin resistance through failure of insulin signaling in liver tissue." (PMID 39328456, 2024). "Consequently, depending on the point of interaction of NLaz with the insulin pathway, loss of NLaz might only improve certain aspects of the insulin-resistance phenotype." (PMID 39033139, 2024). "In this study, elevated insulin and C-peptide concentrations at the age of 6 years were associated with accelerated weight, length, and BMI from infancy and up to 6 years of age, which could result from increased insulin resistance." (PMID 38613059, 2024). "Given that autophagy inhibition blunts insulin signaling in hypothalamic neurons and that consumption of HFDs causes hypothalamic insulin resistance in rodents, we studied whether the increased in immunoproteasome upon PA treatment could play a role in the insulin pathway." (PMID 39095788, 2024). "Additionally, abnormal tau gene expression is associated with impaired insulin signaling, whereas tau phosphorylation may be further enhanced by insulin resistance-induced increases in oxidative stress and inflammation." (PMID 38818523, 2024). "The alternative and conventional hypothesis explains development of T2D with increasing insulin resistance causing exhaustion of pancreatic ß-cells due to over-secretion of insulin, and thus IAPP, too, resulting in subsequent IAPP aggregation and fibril deposition in the pancreas." (PMID 39174611, 2024). "However, under insulin-resistant conditions, there is an overproduction of glucose via gluconeogenesis which is known to significantly contribute to hyperglycemia, a characteristic feature of disorders associated with insulin resistance." (PMID 38745315, 2024). "A close connection between obesity, inflammation, and insulin resistance is further exemplified by the fact that a gradual weight loss of 5–15% of the original body weight over 3–10 months is sufficient to improve β-cell function and insulin sensitivity in all metabolically active tissues." (PMID 38672413, 2024). "However, in individuals with insulin resistance, insulin action is reduced and may even cause vasoconstriction due to increased endothelin production, decreased nitric oxide synthesis and smooth muscle remodelling, including hypertrophy and hyperplasia." (PMID 38542702, 2024).
Insulin resistance (continued). "Taken together, the hierarchical clustering analysis visualized differences in the recruitment of dynamic IR interactors between insulin-sensitive and -resistant cells, which could be potential targets for further investigation into insulin resistance-associated signaling." (PMID 39572596, 2024). "In addition, excessive selenium exposure can lead to hepatic insulin resistance by inducing reverse ROS regulation as well as causing excessive activity of antioxidant enzymes, including selenoenzymes, which can affect insulin secretion by interfering with key redox signaling." (PMID 38877419, 2024). "Despite the fact that diminished differentiation of adipocytes and insulin resistance are strictly associated with type 2 diabetes, type 1 diabetes is chiefly an autoimmune disorder when the immune system erroneously outbreaks and abolishes insulin-generating beta cells." (PMID 38371502, 2024). "For women, because of their higher sensitivity to insulin than men (and thus their lower risk of developing insulin resistance), sex hormones, and consequently facial femininity/masculinity, could be less affected by a large consumption of refined carbohydrates." (PMID 38446775, 2024). "Furthermore, ISO, the main studied metabolite, correlated negatively not only with hepatic fat but also with key body composition measurements and biochemical parameters involved in NAFLD, specifically those associated with insulin resistance, such as insulin and HOMA-IR." (PMID 37996653, 2024). "Insulin resistance may cause, for example, increased plasma insulin levels." (PMID 38397072, 2024). "Whereas glucocorticoids contribute to insulin resistance in both humans and rodents, a low-protein diet, just during the first two weeks of nursing, imprints rat progeny to high peripheral insulin sensitivity associated with functional failure of the pancreatic islets to release insulin." (PMID 39765703, 2024). "In addition, systemic insulin concentrations were lower in the RAP group, suggesting that reduced insulin-secreting capacity may be associated with rapamycin-induced insulin resistance as previously reported." (PMID 39637031, 2024). "We studied Insulin Resistance and Lipid Profile and it’s associated with 25 (OH) vitamin D deficiency among studied cases, Insulin resistance, as indicated by higher levels of fasting insulin and HOMA-IR, was observed in both obese individuals and those with T2DM, compared to the control group." (PMID 39138505, 2024). "Therefore, our findings indicated that individuals with inherited tendency towards dysfunctional insulin secretion may be more susceptible to adverse effects of acquired insulin resistance." (PMID 38555549, 2024). "The elevated lysoPC(15:0) content was causally related to the risk of high uric acid, high insulin, high homeostasis model assessment of insulin resistance (HOMA-IR), dyslipidemia, and overweight/obesity, which shows that abnormal lysoPC metabolism may be connected to the metabolic risk." (PMID 38675462, 2024). "In this respect, other studies conducted in rodent models have described that both maternal and paternal obesity may affect glucose homeostasis, insulin sensitivity, and the lifetime of pancreatic islets in the offspring, thereby predisposing to insulin resistance and type 2 diabetes." (PMID 38238301, 2024). "The chronic exposure of pancreatic β-cells to calorie excess (excessive energy intake) and food additives may increase pancreatic insulin secretion, decrease insulin pulses and/or reduce hepatic insulin clearance, thereby causing chronic hyperinsulinemia and peripheral insulin resistance." (PMID 38791525, 2024). "This improvement in peripheral insulin sensitivity could indirectly benefit brain function by preventing the detrimental effects of hyperglycemia, dyslipidemia, and other metabolic disturbances associated with insulin resistance." (PMID 39337316, 2024).